TNRC6A (trinucleotide repeat containing adaptor 6A)
Description:
Plays a role in RNA-mediated gene silencing by both micro-RNAs (miRNAs) and short interfering RNAs (siRNAs). Required for miRNA-dependent repression of translation and for siRNA-dependent endonucleolytic cleavage of complementary mRNAs by argonaute family proteins. As a scaffolding protein, associates with argonaute proteins bound to partially complementary mRNAs, and can simultaneously recruit CCR4-NOT and PAN deadenylase complexes.
Synonyms: CAGH26; KIAA1460; TNRC6; GW182; FAME6; GW1
Tractability: PROTAC: ubiquitination databases record sites on it.
Gene: Protein-coding gene on chromosome 16 (24,610,209 to 24,827,632, forward strand). Ensembl gene ENSG00000090905.
Subcellular location: Cytoplasm, P-body
Subcellular location (Human Protein Atlas): Golgi apparatus; Nucleoplasm; Vesicles
Pathways (Reactome):
Gene expression (Transcription): Post-transcriptional silencing by small RNAs; RUNX1 regulates genes involved in megakaryocyte differentiation and platelet function; Regulation of NPAS4 mRNA translation; Regulation of RUNX1 Expression and Activity; Transcriptional Regulation by VENTX; Transcriptional regulation by small RNAs
Signal Transduction: Ca2+ pathway; Competing endogenous RNAs (ceRNAs) regulate PTEN translation; Estrogen-dependent gene expression; MAPK6/MAPK4 signaling; MTOR signalling; NR1H3 & NR1H2 regulate gene expression linked to cholesterol transport and efflux; Pre-NOTCH Transcription and Translation; Regulation of PTEN mRNA translation; TGFBR3 expression
Cell-Cell communication: Regulation of CDH1 mRNA translation by microRNAs; Regulation of CDH11 mRNA translation by microRNAs
Cellular responses to stimuli: Oncogene Induced Senescence; Oxidative Stress Induced Senescence
Developmental Biology: Regulation of MITF-M-dependent genes involved in apoptosis
Immune System: Regulation of PD-L1(CD274) translation
Gene Ontology:
Molecular function: protein binding; protein-macromolecule adaptor activity; RNA binding; nucleic acid binding
Biological process: miRNA-mediated gene silencing by inhibition of translation; miRNA-mediated post-transcriptional gene silencing; P-body assembly; miRNA processing; positive regulation of nuclear-transcribed mRNA poly(A) tail shortening
Cellular component: P-body; RISC complex; cytosol; nucleoplasm
Genetic constraint (gnomAD): Loss-of-function variants: 44 observed, 219.77 expected, observed/expected ratio (o/e) 0.2, 90% interval 0.16 to 0.26. The upper end of that interval is the gene's LOEUF score, 0.26, which puts it in group 1 of 6, group 1 being the genes least tolerant of losing a copy. Missense variants: 2,193 observed, 2,460.2 expected, observed/expected ratio (o/e) 0.89, 90% interval 0.86 to 0.92. Synonymous variants: 844 observed, 858.74 expected, observed/expected ratio (o/e) 0.98, 90% interval 0.93 to 1.04.
Homologues: Orthologues: macaque TNRC6A (99% identical), chimpanzee TNRC6A (98% identical), pig TNRC6A (97% identical), dog TNRC6A (96% identical), rat Tnrc6a (94% identical), guinea pig TNRC6A (93% identical), rabbit TNRC6A (92% identical), mouse Tnrc6a (92% identical), zebrafish tnrc6a (53% identical). Paralogues in human: TNRC6C (43% identical), TNRC6B (35% identical), UBXN4 (6% identical), UBAC1 (5% identical), UBXN1 (4% identical).
Diseases named in the same sentence as TNRC6A in open-access papers:
TNRC6A is named in the same sentence as 39 diseases in open-access papers, as found by Europe PMC text mining. Sharing a sentence is not in itself a finding about the gene and the disease. The quoted sentences say what the papers report.
gastric cancer (4 papers, 2011 to 2022). A primary or metastatic malignant neoplasm involving the stomach. "Previously, a number of studies have demonstrated deregulation of miRNA in gastric cancer and the importance of the entire microRNA system has been documented in both gastric and colon cancer by the presence of cancer-specific mutations in the key RISC components AGO2 and TNRC6A." (PMID 21418558, 2011). "We then performed similar BGLF2-FLAG IPs (with RNase A treatment) in AGS gastric carcinoma cells, commonly used to study EBV lytic infection, and again confirmed recovery of Ago2 and TNRC6A." (PMID 35007297, 2022). "A Korean study of 2010 evaluated AGO1, AGO2, TNRC6A, TNRC6C, TARBP2 and XPO5 mutations in colorectal (CRC) and gastric cancers (GC), with or without microsatellite instability." (PMID 23586049, 2013).
colorectal cancer (3 papers, 2018 to 2024). A primary or metastatic malignant neoplasm that affects the colon or rectum. "miRNA-mediated deregulation of TNRC6A has been implicated in gastric and colorectal cancers although knowledge about its role in periodontitis remains scarce." (PMID 35132337, 2022).
non-small cell lung carcinoma (3 papers, 2018 to 2023). A group of at least three distinct histological types of lung cancer, including non-small cell squamous cell carcinoma, adenocarcinoma, and large cell carcinoma. "TNRC6A is an efficient biomarker for diagnosis and prognosis of non-small-cell lung cancer; and target of miR-30a." (PMID 30012096, 2018).
Astigmatism (1 paper, 2023). A type of refraction error associated with abnormal curvatures on the anterior and/or posterior surface of the cornea. "Trio-based exome sequencing identified TNRC6A variants in keratoconus, a genetic disease causing myopia and astigmatism." (PMID 37449273, 2023).
Coronary Heart Disease (1 paper, 2021). "LINC00261 and TNRC6A were upregulated, while miR-522-3p was downregulated in coronary heart disease tissues with MI." (PMID 34239606, 2021).
gastric tumors (1 paper, 2021). "TNRC6A is a component of the miRNA processing machinery also involved in RNA splicing and is frequently mutated in colorectal and gastric tumors with microsatellite instability." (PMID 33886505, 2021).
lung carcinoma (1 paper, 2019). "In lung cancer cells, the RBP TNRC6A binds to and regulates the formation of circ_0006916 accelerating lung cancer cell growth." (PMID 30736838, 2019).
melanoma (1 paper, 2013). A malignant, usually aggressive tumor composed of atypical, neoplastic melanocytes. "The upregulated expression of a few genes (DDX17, MARCH8, TNRC6A) was confirmed by RT-qPCR (using the limited residual RNA/cDNA of 2 of the microarrayed melanoma samples)." (PMID 24098529, 2013).
nasopharyngeal carcinoma (1 paper, 2022). A carcinoma arising from the nasopharyngeal epithelium. "First, we expressed HA-tagged RISC components (Ago2, TNRC6A TNRC6B) with or without BGLF2-FLAG in HONE-1 (EBV-negative nasopharyngeal carcinoma) cells and stained the cells for HA and FLAG." (PMID 35007297, 2022).
periodontitis (1 paper, 2022). An acute or chronic inflammatory process that affects the tissues that surround and support the teeth. "The genes with the highest degrees in shared-DEminRNA-gene network included PTEN, CCND1, MDM2, SCD, and TNRC6A, and these may be important miRNA-deregulated mediators linking H. pylori infection and periodontitis." (PMID 35132337, 2022).
prostate tumour (1 paper, 2023). "We checked the expression levels of CDK6, TNRC6B, AGO1, AGO3, and TNRC6A in PCa tissues, based on data from 465 prostate tumour samples obtained from TCGA-PRAD database, and stratified according to the 2014 ISUP-GG into low-risk (ISUP I and II) and high-risk (ISUP III, IV, and V)." (PMID 37978493, 2023).
prostatic intraepithelial neoplasia (1 paper, 2013). "TNRC6A has been reported to be expressed in 55% of prostatic intraepithelial neoplasia (PIN) and 63.6% of PCa cases." (PMID 23135352, 2013).
ZIKV infection (1 paper, 2024). "To study the impact of ZIKV infection on IGF2BP2 association with endogenous RNAs, we decided to focus our analysis on three known IGF2BP2 mRNA ligands namely CIRBP, TNRC6A, and PUM2." (PMID 39565347, 2024). "More specifically, it has been shown that ZIKV infection decreases m6A content of CIRBP mRNA and increases the one of PUM2 and TNRC6A mRNAs." (PMID 39565347, 2024).
cancer (12 papers, 2011 to 2024). A tumor composed of atypical neoplastic, often pleomorphic cells that invade other tissues. "The most frequently mutated genes were TNRC6A, DICER1, SMAD4 and ZCCHC11, with mutations in 2–3% of pan-cancer samples." (PMID 33406242, 2021). "TNRC6A underexpression in the rapidly growing antler tissues could plausibly represent a mechanism that promotes their cancer-like growth rate or the stem-cell-like behaviors of antler-producing tissues." (PMID 38769090, 2024). "TNRC6A, an essential mRNA-binding protein in miRISC, is inducing the DDRNA expression and functionality; and miR-30 promotes cancer by suppressing TNRC6A." (PMID 33505218, 2021).
tumor (7 papers, 2016 to 2024). "TNRC6A mutations were not present in all samples; however, almost every treatment group had a single tumor sample with this alteration, suggesting it may represent a more general resistance mechanism." (PMID 33886505, 2021). "In our analysis of genetic variants that could contribute to drug resistance, we found a mutation in a splicing factor, TNRC6A, present in at least 1 tumor from all treatment groups but not in the untreated controls." (PMID 33886505, 2021). "We observed significant over-expression of ADAR, ADARB1, DDX5/17/20, DGCR8, DICER1, DROSHA, EIF2C1-4 (AGO1-4), GEMIN4, POLR2A, TARBP2, TNRC6A and XPO5 in tumor tissue compared to adjacent mucosa." (PMID 31510013, 2019). "In addition, the expression of DDX5/20, DGCR8, DICER1, DROSHA, EIF2C1-4, GEMIN4, TNRC6A and XPO5 was deregulated not only in tumor tissue, but also in corresponding liver metastases compared to adjacent tissue." (PMID 31510013, 2019).
infection (2 papers, 2011 to 2019). The state of being infected such as from the introduction of a foreign agent such as serum, vaccine, antigenic substance or organism. "Additionally, we show that the levels of crucial PB proteins (DDX6, AGO2 and TNRC6A) remain unchanged during infection." (PMID 21390246, 2011).
TNRC6A also shares sentences with these, for which no sentence is quoted: autoimmune conditions (2 papers); autoimmune disease (2); colon cancer (2); adult familial myoclonic epilepsies (1); alcohol dependence (1); Alzheimer disease (1); breast carcinoma (1); epilepsy (1); Friedreich ataxia (1); Fuchs endothelial corneal dystrophy (1); genetic disease (1); keratoconus (1); myocardial infarction (1); myopia (1); neuronal intranuclear inclusion disease (1); pancreatic cancer (1); Peptic ulcer (1); prostate carcinoma (1); Sensory neuropathy (1); spinocerebellar ataxia type 37 (1); systemic lupus erythematosus (1); Tinnitus (1); uterine fibroids (1).